GDF15 (growth differentiation factor 15)
Diseases named in the same sentence as GDF15 in open-access papers (continued):
Sharing a sentence is not in itself a finding about the gene and the disease.
tumor (continued). "To check whether GDF-15 also induce muscle atrophy by inducing apoptosis, we observed the activation state of apoptotic pathways in C2C12 myotubes treated with recombinant GDF-15, tumor cell medium, tumor-derived exosomes as well as in GA muscle tissues of tumor-bearing mice." (PMID 35379793, 2022). "In addition, with the condition of cellular stress, GDF-15 and other cytokines produced by fibroblasts, such as granulocyte-macrophage colony stimulating factor, interleukin-12 (IL-12), or chemokine c-x-c motif 12 (CXCL-12), act on nearby cells to promote tumor cell proliferation and tumor growth." (PMID 35508696, 2022). "In addition, both CM presented a remarkable quantity of different proteins that have been associated with antioxidant and/or anti-inflammatory effects and may thus mediate the viability of non-tumor cells, such as AIFM1, ANXA5, CD9, CDH13, GDF15, GSR and TIMP2." (PMID 34884877, 2021). "In addition, we revealed that tumor immune cell contents, such as enriched Th1, enriched Treg, enriched eosinophils, and decreased NKT, may play counteracting roles in the tumor-regulatory activity of the miR-216a/GDF15 axis." (PMID 34948431, 2021). "However, GDF15 cannot exert its protection from tumor growth without intact adaptive immunity." (PMID 32502202, 2020). "Moreover, growth differentiation factor (GDF)-15, a member of the transforming growth factor-beta (TGF-β) superfamily of cytokines, was detected in colorectal carcinoma and glioma tumor specimens, where it contributed to promoting EMT, tumor metastasis, proliferation, and immune escape." (PMID 32120774, 2020). "Thus, except for a dissenting report that found no change in tumor incidence, size, or invasiveness in GDF15-KO mice, experiments with genetic manipulation of GDF15, which alter GDF15 expression before the manifestation of cancerous pathology seem to support an antineoplastic function of GDF15." (PMID 32310257, 2020). "However, genetic ablation of GDF-15 alone had no apparent effect on HCC tumor formation rate, growth rate, or invasiveness; thus GDF-15 may rather exert its effects in context of pro-carcinogenetic networks." (PMID 25826080, 2016). "CircMETTL6 acts as a tumor suppressor by interfering with NONO's interaction with POLR2A, leading to decreased GDF15 transcription." (PMID 39899667, 2025). "We found high levels of GDF-15 in KL mice with CACS compared with WT, CR, and tumor bearing mice without CACS." (PMID 35941104, 2022). "To determine if systemic GDF15 would also protect mice from the growth of TRAMP PCa, we first implanted the prostates of 20 WT mice with tumor cells from TRAMP with a normal immune system and bearing no other genetic modifications, using the OTTEM model." (PMID 32502202, 2020). "However, several activated canonical pathways were not activated in the tumor component of GDF15-KD in comparison to GDF15-NT such as the interferon signaling pathway and cell cycle: G2/M DNA damaging checkpoint regulation pathway, which suggests GDF15 expression may be involved in those pathways." (PMID 33086658, 2020). "To be able to more efficiently study the impact of lack of adaptive immunity on GDF15 mediated reduction in PCa growth, we developed and used Orthotopic TRAMP Tumor Engraftment Model." (PMID 32502202, 2020). "However, these may not always be a good reflection of local availability of GDF15 within the tumor." (PMID 32502202, 2020). "Further, it was notable that this occurred in the face of smaller tumors and lower tumor grades at all stages of disease, suggesting mechanisms independent of the effect of MIC-1/GDF15 on the primary tumor." (PMID 22952779, 2012). "However, differently from experimental models of other tumor histotypes showing a direct effect of GDF-15 on tumor phenotype, siRNA-mediated knockdown of GDF-15 failed to affect proliferative, migratory, and invasive potential of EHE cells." (PMID 39283723, 2024).
tumor (continued). "In addition to the increased levels of a macrophage marker in large tumors, our study suggests an association between the mRNA levels of the cytokines CCL5, CCL18, and GDF15, as well as the transcription factor IRF4, and VS tumor volume, which has not yet been investigated in VSs." (PMID 39272860, 2024). "Notably, GDF-15 may primarily have local effects, depending on its diffusion gradient and biological IC50, thereby excluding immune cells from the tumor microenvironment in the absence of generalized immunosuppression." (PMID 37474523, 2023). "As PD-L1 is a known marker of tumor progression, our findings of the colocalization of PDL1 with GDF-15 in PCa but not in BPH is a novel discovery that could be used in future, prospective studies as biomarkers of malignancy in tissue biopsies or cells/RNA in urine or seminal plasma." (PMID 36230513, 2022).
cardiovascular disease (261 papers, 2011 to 2026). "Growth differentiation factor 15 (GDF15) is a stress-responsive cytokine strongly associated with aging, multimorbidity, and cardiovascular disease." (PMID 41977265, 2026). "In light of these considerations, the aim of the present review is to offer a focused and critical description of the current evidence supporting the diagnostic and prognostic value of GDF-15 in cardiovascular diseases." (PMID 41590509, 2026). "This review summarizes current insights into GDF-15, with emphasis on its quantification methods, biological functions in cardiovascular diseases, and its emerging role as a diagnostic and prognostic biomarker." (PMID 41590509, 2026). "Elevated GDF15 levels are closely associated with cardiovascular disease severity, increased risk of adverse cardiovascular events, and the presence of depressive symptoms." (PMID 41179812, 2025). "Epidemiological studies suggest that elevated GDF-15 levels increase the risk of bleeding in patients with cardiovascular diseases or AF8–10." (PMID 40744929, 2025). "Growth differentiation factor 15 (GDF15) stood out as a risk marker for cardiovascular disease related to aging with increasing expression levels with age." (PMID 40242549, 2025). "While GDF-15 is a biomarker of cardiovascular disease and is also induced by NSAIDs, a direct link and/or cause and effect are unclear and outside the scope of the current study but remains the subject of investigation." (PMID 39660078, 2024). "GDF-15 has been applied as a biomarker for predicting the risk of cardiovascular diseases and cardiovascular events." (PMID 38828460, 2024). "Growth differentiation factor 15 (GDF-15) is a stress-responsive cytokine that regulates myocardial injury, cardiac overloading pressure, and inflammation and is related to the risk of cardiovascular diseases and events." (PMID 38828460, 2024). "The purpose of the study is to investigate the association between DNAm-predicted GDF15 levels and all-cause and cardiovascular disease (CVD) mortality in a nationally representative cohort." (PMID 39625596, 2024). "Today, GDF-15 is considered as a marker of integrated underlying cardiovascular disease burden with higher circulating levels being associated with the presence of atherosclerotic cardiovascular disease." (PMID 37008733, 2023). "Growth differentiation factor 15 (GDF-15), which modulates cellular energy balance, is reported to be positively associated with cardiovascular disease." (PMID 37371667, 2023). "Growth-differentiation factor-15 (GDF-15) is a promising humoral marker for risk stratification in cardiovascular disease." (PMID 37296774, 2023). "GDF-15 is considered as an inflammatory biomarker of cell stress linked to cardiovascular disease in response to myocardial tissue injury." (PMID 35219331, 2022). "It has been established that increased GDF15 levels are associated with an increased risk of cardiovascular disease." (PMID 33567936, 2021). "Xie S, Lu L, Liu L. Growth differentiation factor-15 and the risk of cardiovascular diseases and all-cause mortality : A meta-analysis of prospective studies." (PMID 33566936, 2021). "Although serum levels were higher than pericardial fluid levels, it is possible that only GDF15 that is heart-derived is associated with cardiovascular disease prediction." (PMID 34441356, 2021). "We found that the higher serum level of GDF-15, the greater the risk of cardiovascular disease by chi-square test (Q1: 40%, Q2: 65%, Q3: 70%, and Q4: 85%, P=0.024)." (PMID 34394348, 2021). "In this context, growth differentiation factor-15 (GDF-15) is linked to e.g. cardiovascular diseases and is related to mortality in older adults." (PMID 34920697, 2021). "Some studies have indicated a potential use of GDF-15 as a clinical biomarker for predicting overall cardiovascular disease risk." (PMID 34177769, 2021).
cardiovascular disease (continued). "GDF-15 was an independent risk factor for cardiovascular disease in AGHD patients below 60 years of age after adjusting for other cardiovascular risk factors such as BMI, HOMA-IR, LDL-C, and hs-CRP by binary logistic regression (P < 0.05)." (PMID 34394348, 2021). "This study supports the effect of estradiol on GDF15 expression in women who were at low risk for cardiovascular disease." (PMID 32857481, 2020). "Elevated levels of GDF-15 are strongly associated with cardiovascular disease (CVD), and in large cohorts, GDF-15 has been shown to be an independent predictor of all-cause mortality when adjusted for cardiovascular risk factors, CVD, and other biomarkers." (PMID 32089755, 2020). "It indicated the association of GDF-15 with cardiac remodeling, which was the potentially important pathways in the pathogenesis of cardiovascular disease." (PMID 30819257, 2019). "Previous studies have documented that the association between growth differentiation factor‐15 (GDF‐15) the risk of patients with cardiovascular diseases (CVDs)." (PMID 30697778, 2019). "Growth differentiation factor-15 (GDF-15) is an emerging biomarker for risk stratification in cardiovascular disease." (PMID 29529072, 2018). "In the whole cohort (n= 256) who had rIMT investigated at visit 1, we first examined the relation between rIMT, clinical characteristics and blood biomarkers (NT-proBNP, and GDF-15) known to be associated with cardiovascular disease." (PMID 28881821, 2017). "Growth-differentiation factor-15 (GDF-15) is an emerging humoral marker for risk stratification in cardiovascular disease." (PMID 27717384, 2016). "Growth differentiation factor-15 (GDF-15) has recently emerged as a risk predictor in patients with cardiovascular diseases." (PMID 27311391, 2016). "Additionally, Growth Differentiation Factor-15 (GDF-15) has been recently found to be a measure of chronic pain in MSDs and the risk of cardiovascular disease in patients with CMP." (PMID 40177366, 2025). "Studies have demonstrated that due its association with inflammation, GDF15 may potentially act as a biomarker for cardiovascular disease." (PMID 40278353, 2025). "Although elevated circulatory levels of GDF15 have been associated with chronic inflammatory conditions in various renal, lung, liver, and cardiovascular diseases, its involvement in organ fibrosis began to emerge only in recent studies during the past few years." (PMID 40565178, 2025). "However, to better understand the link between blood levels of GDF-15 and cardiovascular disease, a genetic predisposition to higher levels of GDF-15 needs to be assessed." (PMID 38396781, 2024). "Also, GDF-15 is a stress-response biomarker associated with several types of cardiovascular disease." (PMID 38429673, 2024). "Furthermore, the use of prospective cohorts in some studies posed challenges in distinguishing GDF15-related disease risk directly associated with neurodegeneration as opposed to risks associated with all-cause mortality, infection or cardiovascular disease." (PMID 39737171, 2024). "Taking as a whole, this evidence strongly supports the hypothesis that GDF-15 is a reliable biomarker for cardiovascular risk in patients with metabolic and cardiovascular diseases." (PMID 36614282, 2023). "Nevertheless, additional studies in healthy individuals and patients with cardiovascular disease are needed to further investigate the association of GDF-15 with platelet reactivity and to reveal underlying mechanisms, as well as the clinical relevance of these findings." (PMID 36836162, 2023). "Although increased circulating GDF-15 levels have been closely associated with cardiometabolic disorder and cardiovascular disease, its elevation may also reflect insulin responsiveness and the therapeutic effects of antidiabetic medications." (PMID 35883490, 2022).
cardiovascular disease (continued). "Despite multiple studies strongly linking GDF-15 serum levels with an increased risk of cardiovascular events and death, the specific involvement of the protein in the development of cardiovascular disease is still unknown." (PMID 35872912, 2022). "Furthermore, studies in adults living with HIV infection show associations of high FGF21 or GDF15 levels with lipodystrophy, insulin resistance, cardiovascular disease, and overall mortality." (PMID 34972147, 2021). "The clinical diagnostic significance of circulating GDF-15 in AS patients could be predicted from studies on its role in several cardiovascular diseases and mortality after transcatheter aortic valve replacement." (PMID 33477548, 2021). "The potential association between GDF-15 and cardiovascular disease risk was analyzed." (PMID 34394348, 2021). "Moreover, GDF-15 was an independent risk factor for cardiovascular disease in AGHD patients after adjusting for traditional cardiovascular risk factors." (PMID 34394348, 2021). "Meta-analysis shows that high levels of GDF-15 may increase the risk of mortality in patients with cardiovascular diseases." (PMID 32016113, 2020). "Growth differentiation factor 15 (GDF-15) is strongly associated with cardiovascular disease (CVD)." (PMID 32089755, 2020). "The association of elevated plasma GDF15 with cardiovascular diseases is well-established." (PMID 32671100, 2020). "However, the usefulness of LASSO needs to be confirmed in future studies involving other diseases and risk factors such as some new emerging risk biomarkers in cardiovascular diseases and disorders (e.g., uric acid, growth-differentiation factor-15)." (PMID 30373530, 2018). "This new work attributing modulation of metabolism to GDF15 may provide new insights into its dual predictive values in cardiovascular disease and all-cause mortality." (PMID 29967567, 2018). "Previous studies suggested that GDF-15 might be a risk factor and prognostic biomarker for cardiovascular disease." (PMID 29682097, 2018). "Indeed, elevated MIC-1/GDF15 levels are an important risk factor for cardiovascular disease, as well as a marker of poor outcomes and sub-optimal responses to therapy." (PMID 22514681, 2012). "Growth differentiation factor 15 (GDF15), a distant member of the superfamily of transforming growth factor-β which receptor has recently been discovered, is gaining recognition as a biomarker in cardiovascular diseases (CV) and a predictor of all-cause mortality." (PMID 39008451, 2024). "Furthermore, GDF-15 was associated with CeVD independently of its involvement in cardiovascular disease, but both associations may be mechanistically analogous." (PMID 27537582, 2016). "Gdf15, a member of the TGF‐beta superfamily, is highly upregulated during aging and has been strongly linked to cardiovascular diseases and senescence, making it a key marker of aging and cardiovascular mortality." (PMID 40607964, 2025). "GDF15 has a weak expression in healthy cardiovascular tissue but it dramatically increases in response to specific cardiovascular disease." (PMID 41303556, 2025). "The serum GDF15 levels positively correlated with pathological features of MASLD, an atherogenic lipid profile, and an increased long-term risk of cardiovascular disease." (PMID 40650260, 2025). "Overall, GDF15 appears to have a complex role in cardiovascular disease, acting as both a potential disease amplifier and protector, with further studies required to clarify its mechanisms and physiological significance." (PMID 40837873, 2025). "A body of research has previously indicated that GDF-15 levels can serve as a predictor of adverse outcomes in cardiovascular diseases." (PMID 40430015, 2025). "In cardiovascular disease, GDF-15 is activated in response to ischemic damage and helps by regulating inflammation and preventing mitochondrial dysfunction." (PMID 39781722, 2025).